HCRTR1 (hypocretin receptor 1)
Diseases named in the same sentence as HCRTR1 in open-access papers:
HCRTR1 is named in the same sentence as 93 diseases in open-access papers, as found by Europe PMC text mining. Sharing a sentence is not in itself a finding about the gene and the disease. The quoted sentences say what the papers report.
Anxiety (22 papers, 2015 to 2025). Intense feelings of nervousness, tension, or panic often arise in response to interpersonal stresses. "A recent study in those with panic disorder reported a gene variant linked to ORX system functioning (HCRTR1) is assocaited with increased avoidance and arousal-based anxiety symptoms." (PMID 35918313, 2022). "Whether these relationships are maintained throughout development (i.e., whether VTA Hcrtr1 expression correlates with anxiety-like behavior during adolescence and thermal nociception in adulthood) remains to be determined." (PMID 40247884, 2025). "The increased expression of Hcrt and Hcrtr1 may contribute to the anxiety-like behaviors exhibited by both generations." (PMID 32968044, 2020). "Indeed, Hcrtr1 is highly colocalized with Dbh in the locus coeruleus, and to a lesser extent in the PB and orexin/hypocretin is known to be involved in anxiety states and arousal." (PMID 30210279, 2018). "Here, we demonstrate an increase in VTA Hcrtr1 expression following chronic alcohol exposure that is significantly correlated with anxiety-like behavior, suggesting that higher levels of OX1R expression (and potentially greater VTA OX1R activation) may be linked to higher anxiety-like behavior." (PMID 40247884, 2025).
depression (16 papers, 2014 to 2026). "In human studies, polymorphism in the HCRTR1 gene, a gene that encodes orexin-1 receptors, was positively associated with major depressive disorder." (PMID 41542287, 2026). "An orexin genotype study of patients with depression revealed that a polymorphism (Ile408Val) in the OXR1 gene HCRTR1 significantly differed between cases and controls." (PMID 34942932, 2021). "In summary, we investigated the role of hypocretin system in cognitive impairment in depressive‐like mice and demonstrated that hypocretin‐1 plays an important role in cognitive impairment in depression by regulating the glycolytic pathway and affecting lactate production through HCRTR1." (PMID 39119889, 2024). "Several behaviors in hypocretin 1 (HCRTR1)/OX1R knockout (KO) mice are altered, including minor sleep disturbance, nervousness, depression-like behavior, and a hyperactive alarmed response, as well as reduced locomotor activity, prepulse inhibition, and societal contact." (PMID 36814741, 2023). "hypocretin‐1 model, and hippocampal GFAP‐HCRTR1‐KD model, which demonstrated HCRTR1 affects the reduction of lactate release from hippocampal astrocytes and impairs synaptic plasticity and neurogenesis, thus playing an important role in cognitive dysfunction in depression." (PMID 39119889, 2024). "In depression, hypocretin‐1 may impose an adverse regulatory effect on the hypoxia‐inducible factor‐1α (HIF‐1α) pathway through hypocretin receptor 1, thereby disrupting the glycolytic pathway and resulting in reduced lactate release from astrocytes." (PMID 39119889, 2024). "The docking results of GABRA1 with naringenin and hesperidin, HCRTR1 with naringenin-7-O-glucoside, poncirenin and genipin 1-gentiobioside, and luteolin with SLC6A4, GLO1, MAOB and MTNR1A may clarify the mechanism of action of ZZHPD in treating insomnia and depression." (PMID 35095537, 2021).
narcolepsy (12 papers, 2011 to 2025). A sleep disorder characterized by a tendency for excessive sleepiness during the day which occurs even after adequate sleep in the nighttime. "The HCRTR1 and HCRTR2 genes have been investigated for association with disorders like narcolepsy, Alzheimer’s disease, and headache; in particular, a 408 isoleucine to valine mutation in the HCRTR1 gene (rs2271933) is the most studied SNP." (PMID 38892431, 2024). "The deficiency of neuropeptide orexin/hypocretin or its receptors, OX1R/HCRTR1 and OX2R/HCRTR2 (hereafter OX1R and OX2R for simplicity), results in narcolepsy-like phenotypes, such as abnormal wake to REMS transition and cataplexy, in mice." (PMID 35667851, 2022). "Hcrtr1/OX1R knockout mice show relatively mild abnormalities without frank cataplexy, whereas Hcrtr2/OX2R knockout mice exhibit more severe narcolepsy-like phenotypes, including cataplexy." (PMID 41296378, 2025).
migraine (10 papers, 2011 to 2024). "Genotypic and allelic distribution of 5-HTTLPR and HCRTR1 G1222A, *G29A polymorphisms in migraine patients (MA+MO) compare to control subjects." (PMID 29922128, 2018). "The hypocretin receptor Hcrtr1 is associated with migraine, and Kalirin (Klrn), a Rho guanine nucleotide exchange factor, is required for persistent nociceptive activity dependent synaptic long-term potentiation." (PMID 29422837, 2017). "Polymorphisms in the serotonin transporter gene (SLC6A4) and the hypocretin receptor 1 gene (HCRTR1) may be risk factors for migraine development due to their ability to affect serotonin and hypocretin-1 (HCRT-1) concentrations." (PMID 29922128, 2018). "In particular, it was described that the HCRTR1 gene (orexin/hypocretin receptor 1 gene) may be related to migraine and that the 1246G/A polymorphism of the hypocretin receptor 2 (HCRTR2) gene is significantly associated with headache cluster." (PMID 29541053, 2018). "It seems that HCRTR1 *G29A is more strongly associated with regulating the 5-HT in patients with MA than MO, and therefore may contribute to the early age of onset for migraine." (PMID 29922128, 2018). "Both plasma concentration of 5-HT and localization of HCRTR1 polymorphisms may influence the clinical presence of migraine." (PMID 29922128, 2018). "It seems that G1222A and *G29A polymorphisms in the HCRTR1 gene may be associated with different subtypes of migraine." (PMID 29922128, 2018). "This study supports the hypothesis that the HCRTR1 gene could represent a genetic susceptibility factor for migraine and suggests that the hypocretin system may have a role also in the pathophysiology of migraine." (PMID 23848401, 2013). "Recently, we performed a genetic case–control study to investigate whether genetic variants in the HCRTR1 gene could modify the occurrence and the clinical features of migraine." (PMID 23848401, 2013). "The aim of our study was to investigate whether genetic variants in the hypocretin receptor 1 (HCRTR1) gene could modify the occurrence and the clinical features of migraine." (PMID 21344296, 2011). "Thereby, in order to deepen the analysis of hypocretin system in migraine pathogenesis, we hypothesized that HCRTR1 gene polymorphisms would modify the occurrence and the clinical features of migraine patients." (PMID 21344296, 2011). "However, studies have linked the risk of migraine to SNPs in the HCRTR1 gene." (PMID 38517280, 2024). "Further research is needed to expand on the clinical and biological knowledge of migraine, however, it seems that functional studies of analyzed polymorphisms, especially HCRTR1 *G29A, may bring new information about its role in the pathomechanisms of migraine." (PMID 29922128, 2018). "In conclusion, our data supports the hypothesis that the HCRTR1 gene could represent a genetic susceptibility factor for migraine without aura and suggests that the hypocretin system may have a role in the pathophysiology of migraine." (PMID 21344296, 2011). "Receptors directly associated with migraine or pain include endothelin receptor type B (EDNRB), GIPR, and hypocretin receptor 1 (HCRTR1)." (PMID 35453627, 2022). "We also analyzed the clinical features of migraine in the presence of the S allele of 5-HTTLPRR and the A allele of HCRTR1 G1222A polymorphisms." (PMID 29922128, 2018). "The mean age of migraine onset in individuals with HCRTR1 *G29A was 18 years old for patients with MA and 26 years old for MO patients." (PMID 29922128, 2018). "MA female patients with the GA genotype of HCRTR1 *G29A and the AA genotype of HCRTR1 G1222A developed migraines at 30 years of life." (PMID 29922128, 2018). "Using a case–control strategy we genotyped 384 migraine patients and 259 controls for three SNPs in the HCRTR1 gene." (PMID 21344296, 2011).
migraine (continued). "We observed that the presence of the A allele of HCRTR1 G1222A (AA and GA genotype) had no significant influence on migraine frequency and length of the headache as compared to the GG genotype." (PMID 29922128, 2018). "The strict relation between 5-HT and HCRT-1 may be altered in migraine patients due to different genetic variants of 5-HTTLPR and HCRTR1 G1222A or *G29A." (PMID 29922128, 2018). "According to our preliminary study, performed on a group of 34 migraine patients, both 5-HTTLPR and HCRTR1 G1222A polymorphisms may be associated with 5-HT and HCRT-1 concentrations." (PMID 29922128, 2018). "The localization and type of HCRTR1 polymorphisms (G1222A—missense variant in exon 7, *G29A−3′UTR variant) may predispose patients to the clinical subtype of migraine: MO or MA, respectively." (PMID 29922128, 2018). "The relation between genotypes of 5-HTTLPR, HCRTR1 G1222A, and 5-HT concentrations may bedisturbed in migraine." (PMID 29922128, 2018). "None of the alleles were associated with increased migraine risk, although the A allele of HCRTR1 G1222A (p = 0.0574) and the A allele of HCRTR1 *G29A (p = 0.0647) approached the borderline of significance." (PMID 29922128, 2018). "Interestingly, the majority of MA individuals with GA HCRTR1 *G29A shared the same clinical feature: the early onset of the disease: migraine started before the age of 18." (PMID 29922128, 2018). "Furthermore, we observed lower 5-HT levels in individuals with the GA genotype of HCRTR1 *G29A than in individuals with the GG in all analyzed groups (both migraine and controls)." (PMID 29922128, 2018). "In addition to synonymous SNPs (rs10914456, rs4949449), a non-synonymous HCRTR1 polymorphism of G1222A in exon 7 (rs2271933) encoding an OX1 Ile408Val substitution, has been implicated in migraine." (PMID 24834023, 2014). "The present study of an Italian population provides evidence of a genetic association between a non-synonymous polymorphism (G1222A) in exon 7 of HCRTR1 gene and migraine." (PMID 21344296, 2011). "In conclusion, our data supports the hypothesis that the HCRTR1 gene could represent a genetic susceptibility factor for migraine without aura and that the hypocretin neuronal system may have a role in the pathophysiology of migraine." (PMID 21344296, 2011). "5-HT concentration in MA, MO, both migraine patients (MA+MO) and control subjects regarding different genotypes of 5-HTTLPR, HCRTR1 G1222A, and *G29A." (PMID 29922128, 2018). "HCRT-1 concentration in MA, MO, both migraine patients (MA, MO) and control subjects regarding different genotypes of 5-HTTLPR, HCRTR1 G1222A and *G29A." (PMID 29922128, 2018). "Similarly, the results of the analysis of migraine frequency and length of the headache in group A (AA and GA) and group G (GG) of HCRTR1 G1222A were negative." (PMID 29922128, 2018).
Obesity (10 papers, 2012 to 2025). Accumulation of substantial excess body fat. "Findings include missense variants in established drug targets for sleep disorders (HCRTR1, HCRTR2), genes with roles in arousal (TRPC6, PNOC), and genes suggesting an obesity-hypersomnolence pathway (PNOC, PATJ)." (PMID 33568662, 2021). "We identify 123 loci of which 61 replicate in the 23andMe research cohort, including variants in established drug targets for sleep disorders (HCRTR1, HCRTR2), genes with roles in arousal (TRPC6, PNOC), and genes suggesting an obesity-hypersomnolence pathway (PNOC, PATJ)." (PMID 33568662, 2021).
sleep disorder (6 papers, 2012 to 2024). A change from the patient's baseline sleeping pattern, in the hours slept and/or an alteration/dysfunction in the stages of sleep. "Hypocretin antagonists, especially those that block Hcrtr1 or both Hcrtr1 and Hcrtr2 receptors, have been studied mainly as new drugs for sleep disorders." (PMID 23848401, 2013).
panic disorder (4 papers, 2017 to 2022). An anxiety disorder characterized by multiple unexpected panic attacks with persistent concern of recurring attacks. "Another study in human subjects reported that variations in HCRTR1 gene, which mediates hyperarousal, was associated with the aetiology of panic disorder and agoraphobia." (PMID 35203914, 2022). "Specifically, the presence of HCRTR1 rs2271933 allele was significantly associated with panic disorder/agoraphobia, with the association being particularly strong in female participants." (PMID 35203914, 2022). "Thus, in a multilevel approach, we examined the association between HCRTR1 rs2271933 genotype and panic disorder in two independent samples of patients with panic disorder (PD) with and without agoraphobia (AG) and healthy controls." (PMID 30718541, 2019). "Preclinical studies point to a pivotal role of the orexin 1 (OX1) receptor in arousal and fear learning and therefore suggest the HCRTR1 gene as a prime candidate in panic disorder (PD) with/without agoraphobia (AG), PD/AG treatment response, and PD/AG-related intermediate phenotypes." (PMID 30718541, 2019).
anxiety disorder (3 papers, 2017 to 2023). A category of psychiatric disorders which are characterized by anxious feelings or fear often accompanied by physical symptoms associated with anxiety. "Various other genes have been implicated in the efficacy of CBT/iCBT in treating anxiety disorders, such as Glutamate Receptor, Ionotropic Kainate 4 (GRIK4), Hypocretin/hypocretin receptor 1 (HCRTR1), and Interleukin 1 Receptor Type 1 (IL1R1)." (PMID 37497400, 2023).
colorectal tumors (2 papers, 2017). "In a previous study, primary colorectal tumors and hepatic metastases expressed HCRTR1 mRNA regardless of their location or Dukes stage, whereas adjacent normal colonocytes did not express HCTRTR1 mRNA." (PMID 29100314, 2017).
mood disorder (2 papers, 2012 to 2018). A cognitive disorder a disturbance in which the person's mood is hypothesized to be the main underlying feature. "Interestingly, an association between HCRTR1 and major mood disorders was recently reported." (PMID 22384057, 2012).
psychosis (2 papers, 2021 to 2024). "In rat models of stress-induced psychosis-like behavior associated with DAVTA hyperactivity, HCRTR1/R2-dual antagonism reversed both aberrant DAVTA activity and behavioral correlates of psychosis." (PMID 38123729, 2024).
autosomal dominant polycystic kidney disease (1 paper, 2024). Autosomal dominant form of polycystic kidney disease. "Here, we analyzed orexin-A levels as well as the incidence of SNPs in the hypocretin neuropeptide precursor (HCRT) and its receptors, HCRTR1 and HCRTR2, in 64 patients affected by autosomal dominant polycystic kidney disease (ADPKD) bearing truncating mutations in the PKD1 or PKD2 genes." (PMID 38892431, 2024).
Cognitive impairment (1 paper, 2024). Abnormal cognition is characterized by deficits in thinking, reasoning, or remembering. "Collectively, these findings also provide compelling evidence for the pivotal role of HCRTR1 in hippocampal astrocytes in modulating lactate production, synaptic plasticity, and thereby mitigating depressive‐like behaviors and cognitive impairment." (PMID 39119889, 2024). "In conclusion, HCRTR1 antagonists could potentially mitigate depressive‐like behaviors and cognitive impairment by promoting neural progenitor cells and hippocampal adult neurogenesis." (PMID 39119889, 2024). "However, HCRTR1 antagonists and GFAP‐HCRTR1‐KD both reversed cognitive impairment in CUMS mice." (PMID 39119889, 2024). "Excessive hypocretin‐1 conducted with hypocretin receptor 1 (HCRTR1) reduced lactate production and brain‐derived neurotrophic factor (BDNF) expression by hypoxia‐inducible factor‐1α (HIF‐1α), thus impairing adult hippocampal neuroplasticity, and cognitive impairment in CUMS model." (PMID 39119889, 2024).
cancer (16 papers, 2010 to 2025). A tumor composed of atypical neoplastic, often pleomorphic cells that invade other tissues. "Orexins induce high levels of apoptosis, resulting in a massive reduction in cell growth in various cancer cell lines acting at HCRTR1 or HCRTR2." (PMID 29682090, 2018). "Although HCRTR1 stimulation with high doses of orexin causes apoptosis in colon and prostate cancers, elevated serum orexin level has not been detected in cancer patients." (PMID 29062084, 2017). "As mentioned in the results section, PLD network involves proteins such as LPAR4, LPAR6, HCRTR1, and GRM5, as well as pathways like EGF/EGFR SP, which their roles have been proven in initiation and progression of several cancers." (PMID 29062084, 2017). "Therefore, pharmacologically activated HCRTR1 may be promising in cancer prevention or treatment." (PMID 29062084, 2017).
tumor (7 papers, 2017 to 2024). "Physiologically activated HCRTR1 may activate some pathways other than apoptosis, such as the PLD SP which contributes to tumour progression." (PMID 29062084, 2017).
neurological disorders (4 papers, 2012 to 2025). "Although we used molecular profiling to identify potential targets for the treatment of obesity, the approach we developed to identify Hcrtr1 and CalcR as drug targets is general and could be applied to other neurologic disorders." (PMID 36411386, 2022). "Moreover, some of the candidate genes have previously been linked to psychiatric and neurological disorders (e.g. RORB, HAP1, HCRTR1 and CABP1), further emphasising the potential importance of these candidate genes in the human brain." (PMID 22384057, 2012).
HCRTR1 also shares sentences with these, for which no sentence is quoted: colon cancer (14 papers); insomnia (11); neuroblastoma (6); prostate carcinoma (6); Cataplexy (5); Hypertension (5); pancreatic cancer (4); glioma (3); schizophrenia (3); agoraphobia (2); alcohol dependence (2); Alzheimer disease (2); Anorexia (2); brain injury (2); chronic obstructive pulmonary disease (2); Cluster headache (2); cocaine dependence (2); colitis (2); colorectal cancer (2); esophageal cancer (2); gastric cancer (2); hepatocellular carcinoma (2); hyperglycaemia (2); Insulin resistance (2); liver cancer (2); psychiatric disorder (2); type 1 diabetes (2); adenocarcinoma (1); alcoholism (1); alpha-synucleinopathy (1).
A further 47 diseases each share a sentence with HCRTR1 in 1 paper.